RAD9B (RAD9 checkpoint clamp component B)
Synonyms: FLJ40346
Tractability: No criterion of Open Targets' tractability assessment is met for any kind of drug.
Gene: Protein-coding gene on chromosome 12 (110,501,655 to 110,533,556, forward strand). Ensembl gene ENSG00000151164.
Pathways (Reactome):
DNA Repair: HDR through Single Strand Annealing (SSA); Presynaptic phase of homologous DNA pairing and strand exchange; Processing of DNA double-strand break ends
Cell Cycle: Activation of ATR in response to replication stress; G2/M DNA damage checkpoint
Disease: Impaired BRCA2 binding to RAD51
Gene Ontology:
Molecular function: protein binding
Biological process: cellular response to ionizing radiation; DNA repair; DNA replication checkpoint signaling; mitotic intra-S DNA damage checkpoint signaling; DNA damage checkpoint signaling
Cellular component: nucleus; checkpoint clamp complex; nucleoplasm
Genetic constraint (gnomAD): Loss-of-function variants: 17 observed, 21.58 expected, observed/expected ratio (o/e) 0.79, 90% interval 0.54 to 1.18. The upper end of that interval is the gene's LOEUF score, 1.18, which puts it in group 5 of 6, group 1 being the genes least tolerant of losing a copy. Missense variants: 252 observed, 267.71 expected, observed/expected ratio (o/e) 0.94, 90% interval 0.85 to 1.04. Synonymous variants: 97 observed, 91 expected, observed/expected ratio (o/e) 1.07, 90% interval 0.9 to 1.26.
Homologues: Orthologues: chimpanzee RAD9B (99% identical), macaque RAD9B (87% identical), pig RAD9B (76% identical), guinea pig RAD9B (65% identical), rat Rad9b (63% identical), mouse Rad9b (62% identical), tropical clawed frog rad9b (40% identical), zebrafish rad9b (32% identical), Caenorhabditis elegans hpr-9 (22% identical), Drosophila melanogaster Rad9 (21% identical). Paralogues in human: RAD9A (34% identical).
Diseases named in the same sentence as RAD9B in open-access papers:
RAD9B is named in the same sentence as 4 diseases in open-access papers, as found by Europe PMC text mining. Sharing a sentence is not in itself a finding about the gene and the disease. The quoted sentences say what the papers report.
amyotrophic lateral sclerosis (1 paper, 2021). Amyotrophic lateral sclerosis (ALS) is a neurodegenerative disease characterized by progressive muscular paralysis reflecting degeneration of motor neurons in the primary motor cortex, corticospinal tracts, brainstem and spinal cord. "Differential methylation was reported in RAD9B and C8orf46, CCNF, DPP6, RAMP3, and CCS genes in monozygotic twins and triplets discordant for amyotrophic lateral sclerosis." (PMID 34200232, 2021).
spina bifida (1 paper, 2022). A congenital neural tube defect in which vertebrae are not fully formed. "According to reports, RAD9B is a related gene associated with spina bifida, and its deletion is associated with DNA damage response (DDR)." (PMID 36118578, 2022). "In the study of neural organoids formed by human embryonic stem cells (ESC) with RAD9B deletion, it is found that cell proliferation, differentiation, and cell adhesion are damaged compared with the control group, which is consistent with the phenotype of spina bifida." (PMID 36118578, 2022).
tumor (2 papers, 2020 to 2023). "Furthermore, expression of DNA repair genes LIG4 and RAD9B increased significantly at mRNA level in tumor xenografts." (PMID 32074079, 2020). "In contrast, the expression of ELAVL2, RAD9B and CNOT3, already identified as tumor suppressor, and inhibitors of cell cycle progression, respectively, were upregulated by the miR-Combo." (PMID 37749143, 2023).
RAD9B also shares sentences with these, for which no sentence is quoted: lung carcinoma (1 paper).